TNF (tumor necrosis factor)
Diseases named in the same sentence as TNF in open-access papers (continued):
Sharing a sentence is not in itself a finding about the gene and the disease.
tumor (continued). "Moreover, a study showed that TNF increases GM2 ganglioside expression by enhancing the mRNA levels of GM2/GD2 synthase (β4GalNAc T1) in renal carcinoma, contributing to tumor-induced T-cell death." (PMID 27916834, 2016). "Hence, this study aimed to determine the circulating and tumoural protein expression of TNF-α and the adhesion molecules: L-Selectin and VCAM-1 in primary tumours of PTC patients in relation to their expression in patients with benign thyroid diseases." (PMID 26881177, 2016). "Likewise, chemokines and cytokines are extensively produced in the tumor microenvironment regardless of the initial triggers, and mediators such as IL-1β, TNFα, CCL2 and IL-6 directly promote tumor progression in experimental models of CRC." (PMID 27494857, 2016). "In addition, several inflammatory cytokines, including TNF-α, IL-1, IL-6, TGF-β and IL-18, have been documented to increase HIF-1α expression or transcriptional activation in tumor cells." (PMID 26910835, 2016). "Tumor-derived osteoclastogenic factors, such as interleukin 1 (IL-1), IL-6, parathyroid hormone-related protein (PTHrP), prostaglandin E2 (PEG2), CSF-1 and tumor necrosis factor-α (TNFα) drive an increase in bone resorption." (PMID 27618899, 2016). "The data demonstrated that targeted delivery of TNFα combined with IFNγ by TCP-1 peptide drastically inhibited tumor growth than single treatment and at the same time alleviated systematic toxicity induced by non-targeted TNFα and IFNγ." (PMID 27342639, 2016). "Similarly, in the CT26 tumors, the competency of AH1 tumor antigen-specific CD8+ T cells to produce IFN-γ and TNF-α was increased with combination treatment relative to control or single agent-treated mice." (PMID 27610613, 2016). "Furthermore, in vivo models demonstrate that TNF-α signaling is required for CTL generation and that TNF-α secreted by CTLs directly induces tumor rejection." (PMID 28536374, 2016). "Orally fed iron saturated bLf-Dox inhibited tumour development, prolonged survival, reduced Dox induced general toxicity, cardiotoxicity, neurotoxicity in TRAMP mice and upregulated serum levels of anti-cancer molecules TNF-α, IFN-γ, CCL4 and CCL17." (PMID 27576789, 2016). "Administration of anti-CD40L antibody blocked HCC tumor growth enhancement by Bregs in vivo, blocked enhancement of HCC cell proliferation by Bregs in vitro and decreased IL-10 and TGF-β1 secretion while promoting an increase of TNFα secretion." (PMID 27437104, 2016). "He further characterized the crosstalk between epithelial tumors and the innate immune response, demonstrating that the TNF-Toll non-cell-autonomous signaling cascade dictates tumor cell fate." (PMID 26758990, 2016). "Therefore, we further investigated the affect of hyperbaric oxygen on the expression of IL‐1, TNFα, and other factors including HIF‐1α, NF‐κB, VEGF, and MMP9, which were closely related to tumor development." (PMID 27734611, 2016). "In addition to inducing tumor apoptosis, TCP-1/TNFα or TCP-1/IFNγ also increased the infiltration of CD8+ and CD4+ T cell in the tumor leading to enhanced antitumor immunity." (PMID 27342639, 2016). "In addition, the combination of ascophyllan and OVA promoted tumor-infiltration of OVA specific T cell that potently produced IFN-γ and TNF-α." (PMID 27008707, 2016). "In the gut, TNF-α promotes DAPK-induced apoptosis in tumor cells, whereas normal intestinal epithelial cells are resistant to TNF-α, but are subject to remarkable DAPK-induced inflammation." (PMID 26769850, 2016). "In fact, several studies have shown that TNF-α, IL-1, IL-6 and interferon gamma (IFN-γ), released by both tumor cells and the host in response to the tumor may lead to activation of different pathways of intracellular protein degradation." (PMID 27330885, 2016). "Furthermore, conditioned media from STAT3β-expressing B16 tumor cells induced proinflammatory mediators nitric oxide (NO) and RANTES in peritoneal macrophages and TNF-α in neutrophils." (PMID 27148255, 2016).
tumor (continued). "Cells from the 148I tumor were also relatively resistant: these cells responded to all concentrations of SM-164 or GDC-0152, but only when co-treated with high concentrations of TNFα." (PMID 27129149, 2016). "Moreover, IFN-γ and TNF levels produced by LDLN increased in the presence of LM3 cells, thus indicating a tumor-specific cellular immune response." (PMID 26973649, 2016). "On the other hands, both TNF-α preactivated AD-MSCs with or without irradiation prevented metastasis in ling and liver, and increased apoptosis in tumor mass." (PMID 27329316, 2016). "In fact, AT is recognized now as potent endocrine organ by secreting pro-inflammatory cytokines [such as tumor necrosis factor-alpha (TNF-α) and interleukin-6 (IL-6)] and adipokines (such as leptin) in the tumor microenvironment, with great significant impact on both tumor and immune cells." (PMID 27066006, 2016). "TNF is important for MDSC development, in turn, MDSCs play a crucial role in tumor progression." (PMID 27148266, 2016). "Besides direct killing of tumor cells, NK cells can secrete TNF-α and IFN-γ to drive the Th1 polarization in the tumor microenvironment to further strengthen adaptive cytotoxic responses to tumor cells." (PMID 27785129, 2016). "Furthermore, a tumor-specific production of IFN-γ and TNF as well as tumor-specific IFN-γ-producing CD8 T cells (CD8+IFN-γ+) were found in the celiac and portal lymph nodes of Salmonella-treated mice." (PMID 26973649, 2016). "Because the attachment of tumor cells to endothelial blood vessels is an early event required for transendothelial migration and hence for metastasis, we tested the effect of RCE on the ability of MDA-MB-231 cells to adhere to TNF-α stimulated HUVECs." (PMID 26888313, 2016). "Increased metastasis in EMT6 tumor bearers was seen in vivo following adoptive transfer of serum, or serum‐derived exosomes, from 4THM tumor bearers, an effect which was attenuated by anti‐IL‐6, and anti‐IL‐17, but not anti‐TNFα, antibody." (PMID 26725371, 2016). "In addition, the expression of TNF-α was examined in the TMA and a significant higher level was found in tumor specimens than that in normal specimens (P = 0.002)." (PMID 27356745, 2016). "Lin and Karin reported that IL-10 could modulate apoptosis and suppress angiogenesis during tumor regression, downregulating VEGF, TNF-α, and IL-6 production by TAMs." (PMID 26989335, 2016). "Although TNF-α was initially identified by its ability to kill tumor cells, most normal and tumor cells do not undergo cell death in response to this cytokine." (PMID 26491219, 2015). "Without the disturbing effects of TNF-α, the ECs monolayer can maintain its integrity and hinder the adhesion of the tumor cells." (PMID 26631692, 2015). "The increased immunization dosage shows a significant impact on the length but not the collective magnitude of Interferon gamma (IFNG) and Tumor Necrosis Factor alpha (TNF α) in the tumor microenvironment." (PMID 26048402, 2015). "Rapid reconstitution of anti-tumor recognition and enhanced tumor infiltration of treated NK cells was monitored by 24 h co-incubation of HNSCC tumor spheroids with cetuximab (1 μg/ml) and was characterized by increased IFN-γ and TNFα secretion." (PMID 26579120, 2015). "This therapy is used in patients who have not responded to anti-TNF therapy or for patients with contraindications to treatment with anti-TNF therapy (e.g. various neoplastic diseases)." (PMID 25914745, 2015). "PARN, a major deadenylase in mammalian cells, can potentially act as a tumor suppressor, given that it is activated by the tumor-suppressor BARD1 and it is involved in the degradation of IL-8, VEGF, c-jun, uPA, c-fos and TNF-alpha mRNAs, the levels of which are generally increased in cancers." (PMID 26541675, 2015).
tumor (continued). "In supernatants of HPV-positive tumors upon PMA and ionomycin stimulation we detected higher levels of IL-10, IL-17, IL-21, TNFα and IFNγ compared to supernatants of HPV-negative tumor samples; however, only the levels of IL-17 showed statistically significant differences (p = 0.030)." (PMID 25949860, 2015). "In most cases, TNFα acts as a promoter rather than a killer in tumor cells and tissues because of its abnormally elevated survival functions." (PMID 26156677, 2015). "Presumably this is mediated by the fat body signalling to increase the release of TNFα on the tumour by hemocytes, but the molecules used are not known." (PMID 25948885, 2015). "Mediators of inflammatory pathways such as interleukin-6 (IL-6), tumor necrosis factor alpha (TNFα), and cyclooxygenase-2 (COX-2) are involved in cancer-related mechanisms that diminish tumor suppressor function, stimulate oncogene expression, and increase cell cycling." (PMID 25866823, 2015). "Furthermore, the levels of the cytokines GM-CSF and TNF-α, and the chemokine MCP-1 were much higher in tissue lysates from peritumoural tissues compared with tumour tissues." (PMID 26581194, 2015). "To investigate whether tTF-pHLIP induces an innate immune response, we assessed IL-6, IP-10, TNF-α and IFN-α serum concentrations of non-tumor-bearing C57BL/6 mice before and after tTF-pHLIP treatment." (PMID 26143637, 2015). "Serum levels of TNF-α were markedly reduced in tumour-free but not tumour-bearing TNFR−/− chimeras, consistent with MEK1 activation in epidermal tumour cells driving NF-κB activation." (PMID 25575023, 2015). "To determine if TNF-α can potentiate antitumor effectiveness of electrochemotherapy with intravenous CDDP injection in vivo, we evaluated the effect of intratumoural TNF-α injection before or after electrochemotherapy on tumour growth." (PMID 25810699, 2015). "Tumor antigen-specific T cell-IFN-γ and TNF-α production, as well as cytotoxic ability, were all reduced in mice with impaired T cell-NF-κB, suggesting an important role for this transcription factor in the effector differentiation of tumor-specific effector T cells." (PMID 25648675, 2015). "Additionally, enhanced cytokine (TNFα and IFN-γ) release was observed compared to low cell lysis of the same effector cells co-cultured with untreated tumor cells." (PMID 26579120, 2015). "However, these direct anti-tumor effects can be attributed not only to cytotoxicity but also to their cytokine-producing capacities (IFN-γ, TNF-α, IL-10)." (PMID 25674087, 2015). "Like TNF-α, IL-6 facilitates tumor development by promoting the conversion of non-cancer cells into tumor stem cells in low-attachment culture conditions by up-regulating Oct 4 gene expression through activating the IL-6R/JAK/STAT3 signaling pathway." (PMID 26418748, 2015). "Because we have previously shown that the TPV 2L binds to human TNF but not mouse TNF, the ablation of 2L in some of the recombinant viruses described here was not expected to be a significant factor in tumor clearance." (PMID 25887490, 2015). "IL-16 and TNF-α were undetectable in all cell culture supernatants (data not shown), but was secreted in both tumour tissues (IL-16: 5337 ± 33 and 3121 ± 94 pg/ml respectively, TNF-α: 0.30 ± 0.11 and 1.07 ± 0.17 pg/ml respectively)." (PMID 26183281, 2015). "Consequently, cetuximab is a powerful stimulus of NK cell-mediated ADCC via activation of FcγRIIIa against cetuximab-coated tumor cells and for induction of cytokine release, especially IFN-γ and TNFα secretion." (PMID 26579120, 2015). "This synergistic interaction cannot be attributed to TNF-α cytotoxicity to tumour cells due to the lack of the effect in vitro." (PMID 25810699, 2015). "Thus, most of the parameters evaluated (tumor growth, NAG activity, VEGF, TNF-α production) were higher in inflammation-promoted tumor groups when compared with tumors grown in the subcutaneous space without additional inflammatory support from the sponge." (PMID 26158775, 2015).
tumor (continued). "Notably, injections of IFN-α2, IFN-γ, TNF-α and IL-2 markedly improved the anti-tumor effect of ACT, while treatment with GM-CSF resulted in stimulation of tumor growth." (PMID 26107883, 2015). "Characterization of cytokine expression patterns in these accumulated myeloid splenocytes in tumor bearing mice revealed a Th2 dominant pattern with decreased IL-2, IL-12, interferon (IFN)-γ and tumor necrosis factor (TNF)-α and elevated IL-4 and transforming growth factor (TGF)-β." (PMID 26690220, 2015). "Thus, an increase in TNF-α levels in combination with oxidative stress (i.e., PDT) is likely to have detrimental effects on tumor cell survival." (PMID 26307977, 2015). "Although sex did not have impact on tumour recurrence, both serum IL-6 and TNF-α were higher in men." (PMID 25858079, 2015). "Inflammatory cytokines, such as IL-6 and TNF-α, are produced by tumours and by nonfat cells residing in AT in addition to adipocytes." (PMID 26508820, 2015). "hCG was incapable of inducing the secretion of IL-6 or TNF-α from tumor cells (data not shown) or from PBAC." (PMID 26608647, 2015). "TNFα also helps to remodel tumor microvasculature lacking the factors needed for CTL attachment and extravasation: P and E-Selectins, ICAM-1, VACM-1." (PMID 25592450, 2015). "Similarly tumor necrosis factor-α (TNF-α), secreted by infected keratinocytes and recruited immune cells, has been shown to suppress E6 and E7 and has direct anti-tumor effects through cell cycle arrest." (PMID 26239127, 2015). "Moreover, the medium supernatants of those incubated samples (PP-cultured NK cells and cetuximab-coated HNSCC tumor spheroids) revealed significantly increased IFN-γ and TNFα secretion levels (24 h PP + 1 μg/ml Cetmab + 24 h HNSCC tumor spheroids)." (PMID 26579120, 2015). "This is illustrated by the finding that extensively damaged tumor cells (60 μM ZnPC-ETL group) no longer secrete TNF-α and CCL2." (PMID 26307977, 2015). "In LV-ARsh xenografts, CD8+ T cells have higher expression of IFN-γ, TNF-α and perforin than those in non-transfected xenografts and LV-scramble xenografts, suggesting AR knockdown promoted anti-tumor activity of CD8+ T cells." (PMID 26451607, 2015). "TNF-α is generated by a variety of immune and non-immune cells such as T-cells, NK cells, macrophages and tumor cells, endothelial cells, mast cells, neurons, and fibroblasts." (PMID 26528286, 2015). "IL-6, but not tumor necrosis factor-α, was elevated in male mice harboring W4P-induced tumor, and was reduced by estrogen." (PMID 25645622, 2015). "We therefore propose that tumor cells secrete TNF, which induces CCL2 production in two microenvironment cells (myofibroblasts and macrophages) promoting tumor migration, invasion and extravasation and monocyte recruitment and differentiation into tumor associated macrophages." (PMID 26327448, 2015). "Regardless of the stage of tumor growth, the injection of conjugates increased serum concentrations of IL-6, TNF-α, IFN-γ and IL-12p70." (PMID 26327508, 2015). "Similar to the effects seen in BMDMs, peritoneal macrophages from 4T1 tumor-bearing mice exhibited significantly strengthened production of IL-6 and moderately increased production of CCL2 and TNFα in response to LPS when compared to macrophages from control mice." (PMID 26177198, 2015). "It is possible that in our model monocytes and moDCs exerted some direct antitumor activity via iNOS and TNFα, as these factors were expressed by monocytes and moDC in the dLN and also in the tumor (data not shown)." (PMID 26635798, 2015). "As expected, the involvement of tumor microenvironment in cancer and in its complications, such as DVT, is emphasized in the correlation between plasma levels of IL-6,TNF-α, IL-1β, VEGF and MMP-9 from cancer patients with and without DVT and those released from monocytes." (PMID 26192925, 2015).
tumor (continued). "After 4 h, all tumour secreted-proteins induced a significant increase in surface E-selectin at either higher concentrations tested (CC, IGFBP-7) or over the whole concentration range (CL, VEGF-A, TNF-α)." (PMID 26407999, 2015). "It seems that membrane bound TNF-alpha, rather than soluble TNF-alpha, has the ability to activate MDSCs, known to be involved in tumor neo-vascularization." (PMID 32309563, 2015). "As with the human tumor cells, mouse primary epithelial cells expressed AID upon exposure to TNF-α." (PMID 26282919, 2015). "However, blockage of cytokine IL-6 or TNF-α signaling or inhibition of NF-κB, STAT3, or cyclinD1 expression reduced the average tumor volume (p < 0.05)." (PMID 25823926, 2015). "In addition to reduced tumour growth, expression of proangiogenic/proinflammatory factors like VEGF and TNF-alpha was affected by pK1-5." (PMID 24895598, 2014). "In tumor cells, it is TLR4 that is activated by TNF-α, via TIR-domain-containing adapter-inducing interferon-β (TRIF) dependent pathway, forming a feed-forward loop with TNF-α, which triggers the release of these cytokines." (PMID 25411122, 2014). "Cellular proliferation at an enhanced rate at tumor sites gives rise to hypoxia, low concentration of oxygen that stabilizes HIF-1α, which activates NFκB to secrete an angiogenic protein, VEGF and also induces expression of IL-12 and TNF-α." (PMID 24782866, 2014). "For this purpose, cryopreserved PBMC were thawed and stimulated with a panel of cognate tumor- or viral antigens and their ability to produce key cytokines (i.e. IFN-γ, IL-2 and/or TNF-α) and to express the cytolytic marker perforin were assessed using polychromatic flow cytometry." (PMID 24726012, 2014). "The increase of several immune cell-derived factors, such as interleukin-1 (IL-1), IL-6, IL-8, IL-10, and tumor necrosis factor alpha (TNF-α), has been described in tumor microenvironment: they sustain inflammatory process, contribute to tumor progression, and also exert proangiogenic activity." (PMID 24949467, 2014). "It was in our interest to investigate whether inhibition of HO-1 in tumor cells increased the production of IFN-γ and TNF-α in the population of CD107a + NK-92 cells in our study." (PMID 25302050, 2014). "RT-qPCR analysis indicated that the expressions of the proinflammatory cytokines (TNF-α, IL-6, and IL-1β) and TLR4 of tumor tissues from group 2 were markedly increased at mRNA level after LPS treatment, compared with those of group 1 or 3 without LPS treatment." (PMID 25179302, 2014). "NK cells may also induce the apoptosis of AML blasts and contribute to amplify the anti-tumour immune response through the release of proinflammatory cytokines such as IFN-γ and TNF-α." (PMID 24919191, 2014). "It was found that SMAC mimetics allow sensitization of tumor cells for apoptosis induction by releasing caspases from the inhibitory interaction with IAP proteins, particular XIAP and that SMAC mimetics have complex effects on NFκB and TNF signaling." (PMID 25101252, 2014). "Same as the neutrophils from naive mice, the tumor-promoting neutrophils could produce more IL-18, and express higher levels of NK-activating ligands RAE-1, MULT-1, and H60 after priming by IFN-γ and TNF-α." (PMID 25587026, 2014). "Modest increases in both IFN-γ and TNF-α production were also seen; however, high production of these cytokines by tumor-infiltrating CD8+ T cells was already observed without treatment." (PMID 24829760, 2014). "Because TNF-α, MCP-1, and IP-10 are important indicators of LLLT-induced M1 polarization, LLLT may promote anti-viral and anti-tumor immunity but enhance autoimmune and rheumatoid diseases." (PMID 24692853, 2014). "Other cytokines analyzed (GM-CSF, IL-2, IL-4, IL-10, IL-12 (p70), IL-13, IL-17, VEGF and TNFα) were below detection level of the assay, or did not exhibit any significant changes upon tumor growth or Delta24-RGD treatment (results not shown)." (PMID 24866126, 2014).